PHF14 (PHD finger protein 14)
Description:
Histone-binding protein. Binds preferentially to unmodified histone H3 but can also bind to a lesser extent to histone H3 trimethylated at 'Lys-9' (H3K9me3) as well as to histone H3 monomethylated at 'Lys-27' (H3K27ac) and trimethylated at 'Lys-27' (H3K27me3) (By similarity). Represses PDGFRA expression, thus playing a role in regulation of mesenchymal cell proliferation (By similarity). Suppresses the expression of CDKN1A/p21 by reducing the level of trimethylation of histone H3 'Lys-4', leading to enhanced proliferation of germinal center B cells (By similarity).
Synonyms: KIAA0783
Tractability: PROTAC: UniProt records ubiquitination sites on it; ubiquitination databases record sites on it; its protein half-life has been measured.
Gene: Protein-coding gene on chromosome 7 (10,973,336 to 11,169,623, forward strand). Ensembl gene ENSG00000106443.
Subcellular location: Nucleus (Isoform 1); Chromosome; Cytoplasm (Isoform 2)
Subcellular location (Human Protein Atlas): Vesicles; Cytosol; Nucleoplasm
Gene Ontology:
Molecular function: histone binding; protein binding; histone reader activity; zinc ion binding
Biological process: germinal center B cell differentiation; lung alveolus development; negative regulation of cell population proliferation; negative regulation of mesenchymal cell proliferation; negative regulation of mesenchymal cell proliferation involved in lung development; negative regulation of platelet-derived growth factor receptor-alpha signaling pathway; negative regulation of transcription by RNA polymerase II; chromatin organization
Cellular component: chromosome; cytoplasm; nucleus
Genetic constraint (gnomAD): Loss-of-function variants: 20 observed, 43.29 expected, observed/expected ratio (o/e) 0.46, 90% interval 0.32 to 0.67. The upper end of that interval is the gene's LOEUF score, 0.67, which puts it in group 2 of 6, group 1 being the genes least tolerant of losing a copy. Missense variants: 479 observed, 534.53 expected, observed/expected ratio (o/e) 0.9, 90% interval 0.83 to 0.97. Synonymous variants: 191 observed, 181.47 expected, observed/expected ratio (o/e) 1.05, 90% interval 0.94 to 1.19.
Homologues: Orthologues: chimpanzee PHF14 (100% identical), macaque PHF14 (99% identical), pig PHF14 (98% identical), dog PHF14 (98% identical), mouse Phf14 (96% identical), rat Phf14 (96% identical), guinea pig PHF14 (89% identical), rabbit PHF14 (89% identical), tropical clawed frog phf14 (76% identical), zebrafish phf14 (73% identical), Drosophila melanogaster CG15439 (34% identical), Caenorhabditis elegans phf-14 (13% identical), and 1 more. Paralogues in human: BRD1 (19% identical), BRPF3 (19% identical), BRPF1 (18% identical), JADE2 (15% identical), JADE1 (15% identical), JADE3 (15% identical), MLLT10 (14% identical), MLLT6 (13% identical).
Diseases named in the same sentence as PHF14 in open-access papers:
PHF14 is named in the same sentence as 47 diseases in open-access papers, as found by Europe PMC text mining. Sharing a sentence is not in itself a finding about the gene and the disease. The quoted sentences say what the papers report.
biliary tract cancer (7 papers, 2013 to 2023). "For example, it is believed that, PHF14, as an inhibitor, can not only improve colon cancer, but also play an important role in biliary tract cancer (BTC)." (PMID 37007943, 2023). "As an integral member of the newly discovered PHD family, PHF14 has been found to be responsible for multiple carcinogenesis and development, including colon cancer, biliary tract cancer, lung and bladder cancer." (PMID 37007943, 2023). "Expression of PHF14 was appeared to be correlated in several cancer models such as biliary tract cancer (BTC), colon cancer, and lung cancer." (PMID 31040906, 2019). "Recently, the homozygous deletion of PHF14 has also been identified in a human biliary tract cancer cell line (OZ)." (PMID 28160558, 2017). "PHF14 homozygous deletion has been identified in the human biliary tract cancer cell line OZ and a bi-allelic inactivating mutation is present in human colon cancer HCT-116 cells, suggesting aberrant PHF14 expression may play a role in several tumor types." (PMID 36359362, 2022). "PHF14 is overexpressed in lung and biliary tract cancer and downregulated in colon cancer." (PMID 31798343, 2019). "Several researchers have demonstrated that PHF14 is overexpressed in biliary tract cancer and lung cancer and may also be involved in tumorigenesis." (PMID 30940184, 2019). "Its absence in a colon cancer cell line and a biliary tract cancer cell line may suggest PHF14 plays different roles in different cells/cancer types." (PMID 28160558, 2017). "Moreover, PHF14 could inhibit growth of mesenchymal cells in biliary tract cancer." (PMID 31798343, 2019). "As the expression level of PHF14 in colon cancer/biliary tract cancer patients is not clear, the clinical relevance of these findings remain to be elucidated." (PMID 28160558, 2017).
colon carcinoma (7 papers, 2013 to 2023). "A mutation in PHF14 was previously identified in a colon cancer cell line." (PMID 23833654, 2013). "Analysis of TCGA colon cancer (n=461) and skin cancer (n=470) datasets revealed a positive correlation between PHF14 expression and protein translation initiation factors, eIF4E, eIF4B, and RPS6." (PMID 31040906, 2019). "In a colon cancer cell line HCT-116, a bi-allelic inactivating mutation of PHF14 has been identified." (PMID 28160558, 2017). "This SNP is near Phf14, a nuclear phosphoprotein that may function as a colon cancer tumor suppressor." (PMID 24386469, 2013). "While PHF14 depletion has been shown to suppress cell proliferation in lung cancer cells and bladder cancer cells, its overexpression constrained BTC cells growth and improved prognosis in colon cancer." (PMID 31798343, 2019).
lung carcinoma (6 papers, 2017 to 2023). "PHF14 has been reported as a potential diagnostic marker of lung cancer as its overexpression is inversely correlated with carcinogenesis and poor survival." (PMID 31040906, 2019). "In line with our findings, depletion of PHF14 suppressed cell proliferation in several lung cancer cells although its respective role was associated with mitotic defect not G1-S phase arrest." (PMID 31040906, 2019). "The high expression level of PHF14 was associated with adenocarcinoma and poor survival in lung cancer patients." (PMID 28160558, 2017). "Using various analyses, we found that more than 70% lung cancer tissues exhibited overexpression of PHF14, which was significantly associated with shorter survival in lung cancer patients." (PMID 28160558, 2017). "The high expression level of PHF14 in early cancer samples makes it a promising early diagnostic marker in lung cancer." (PMID 28160558, 2017). "PHF14 is highly expressed in lung cancer, and its high expression is associated with poor survival." (PMID 36803146, 2023). "This may indicate other unidentified functions of PHF14/ different isoforms or mutations of PHF14 in lung cancers." (PMID 28160558, 2017). "Interestingly, stable knockdown of PHF14 in lung cancer cells seems to cause a downregulation of KIF4A, which may indicate an intrinsic functional regulation between the two proteins." (PMID 28160558, 2017). "Here, we found that PHF14 was co-overexpressed with KIF4A in lung cancers and the two proteins formed a functional complex involved in cell mitosis and tumorigenesis." (PMID 28160558, 2017). "To investigate the possible role of PHF14 in lung cancer, we chose two lung adenocarcinoma epithelial cell lines with high expression of PHF14, A549 and CRL-5810, for further study." (PMID 28160558, 2017). "Two small interfering RNA fragments (siRNA/PHF14-297i and siRNA/PHF14-1958i) targeting human PHF14 were transfected into lung cancer cells respectively and led to efficient suppression of endogenous PHF14 expression." (PMID 28160558, 2017). "Depletion of PHF14 inhibited lung cancer cell colony formation in soft agar and tumor formation in nude mice." (PMID 28160558, 2017). "PHF14 increases mitotic defects and DNA errors in lung cancer model." (PMID 31798343, 2019). "In addition, qPCR analysis showed significant higher mRNA expression levels of PHF14 in 71% (17/24) of human lung cancer specimens." (PMID 28160558, 2017). "In addition to the co-overexpression in lung cancer cells, PHF14 and KIF4A form a functional complex in native cells." (PMID 28160558, 2017). "Our data provide new insights into the biological significance of PHD finger proteins and imply that PHF14 may be a potential biomarker for lung cancer." (PMID 28160558, 2017). "Furthermore, the high PHF14 expression level was significantly correlated with poor survival in lung cancer patients." (PMID 28160558, 2017). "In the present study, we found that PHF14 was highly expressed in lung cancer." (PMID 28160558, 2017). "In addition, 83% (39/47) of the lung cancer patients with small tumor size (≤3 cm) demonstrated PHF14 overexpression." (PMID 28160558, 2017). "So far, pronounced dysregulation of PHF14 has only been found in lung cancer." (PMID 28160558, 2017). "Knockdown of PHF14 in cancer cells strongly inhibited cell proliferation, transformation, and tumor formation in nude mice, supporting an important function of PHF14 in promoting the carcinogenesis of lung cancer." (PMID 28160558, 2017). "Interestingly, upregulation of PHF14 (score ≥ 9) were detected in a significant proportion (76%, 19/25) of early stage lung cancer patients (TNM I), which indicated its role in early carcinogenesis." (PMID 28160558, 2017). "Interestingly, high expression of PHF14 can be detected not only in advanced lung cancer patients, but also at early stage (TNM I) and in small size tumor (≤3cm)." (PMID 28160558, 2017).
lung carcinoma (continued). "In this study, we found that PHF14, a newly identified PHD finger protein, is highly expressed in lung cancer." (PMID 28160558, 2017). "We noted that the expression patterns of PHF14 and KIF4A in these lung cancer samples are quite the same." (PMID 28160558, 2017). "And similar to PHF14, KIF4A has been related to poor prognosis in lung cancers." (PMID 28160558, 2017). "The novel PHF14/KIF4A complex might indicate a fundamental interdependent role for PHF14 and KIF4A in the carcinogenesis of lung cancer." (PMID 28160558, 2017). "In this context, we found that PHF14 was significantly upregulated in LAD tissues collected in the TCGA LUAD datasets, as compared with the normal tissue specimens, which include 59 pairs of lung cancer/normal tissues and 517 cases of lung cancer vs 59 cases of unpaired normal lung tissue." (PMID 37072414, 2023).
gastric cancer (5 papers, 2020 to 2025). A primary or metastatic malignant neoplasm involving the stomach. "PHF14 can promote lung adenocarcinoma metastasis and promotes cell proliferation and migration in gastric cancer cells." (PMID 40666499, 2025). "Because of the essential role of AKT and ERK1/2 pathways in cell proliferation as well as in cancer development, inhibitors against PHF14 can be explored for gastric cancer therapy." (PMID 32596345, 2020). "In order to determine the role of PHF14 in gastric cancer, an IHC assay was performed and results revealed that PHF14 is highly expressed in gastric cancer samples compared with adjacent peritumor gastric tissues." (PMID 32596345, 2020). "Further, we checked the expression of PHF14 in 3 gastric cancer cell lines as well as in a gastric epithelial cell line." (PMID 32596345, 2020). "Meanwhile, this study indicates that PHF14 serves as a potential biomarker for tumor diagnosis, prognosis, and therapy in gastric cancer." (PMID 32596345, 2020). "Furthermore, knocking down of PHF14 inhibits cell proliferation as well as tumorigenesis in gastric cancer." (PMID 32596345, 2020). "In order to investigate whether PHF14 is involved in migration and invasion in gastric cancer cells, a migration assay and invasion assay were performed." (PMID 32596345, 2020). "PHF14 is highly expressed in tumor tissues and in cell lines, which reminder us that PHF14 may be regarded as a biomarker in diagnosis of gastric cancer." (PMID 32596345, 2020). "PHF14 is therefore regarded as a promising therapeutic target in gastric cancer." (PMID 32596345, 2020). "This suggests that PHF14 can be utilized as a prognostic marker in gastric cancer." (PMID 32596345, 2020). "This study is mainly focused on the importance of PHF14 in gastric cancer cells." (PMID 32596345, 2020). "PHF14 was knocked down in two gastric cancer cell lines, HGC-27 and MKN-45 (Figures." (PMID 32596345, 2020). "This study shows that PHF14 accelerates tumorigenesis in gastric cancer." (PMID 32596345, 2020). "Attenuation of PHF14 inhibits cell proliferation in gastric cancer cells." (PMID 32596345, 2020). "This study indicates that PHF14 serves as a tumor promoter in gastric cancer." (PMID 32596345, 2020). "Moreover, higher level of PHF14 indicates lower survival in patients suffering from gastric cancer." (PMID 32596345, 2020). "This study aims to explore whether PHF14 plays an important role in gastric cancer." (PMID 32596345, 2020). "Further to screen several circRNAs from PHF14 for function, it was found that circPHF14 was essential for the growth and tumorigenesis of DDX5-positive gastric cancer cells." (PMID 36996491, 2023). "A latest study indicates that silencing PHF14 induces apoptosis in glioblastoma cells; however, there is no apoptosis in gastric cancer cells after knocking down of PHF14, which remind us that PHF14 plays different roles in different cancers." (PMID 32596345, 2020). "The expression of PHF14 enhances no matter in clinical samples or in gastric cancer cells." (PMID 32596345, 2020).
bladder cancer (4 papers, 2019 to 2023). "Meanwhile, the regulation of the LINC00612/miR-590/PHF14 axis in bladder cancer requires confirmation in large-scale clinical research studies, which will be the main aim of a future study." (PMID 30940184, 2019). "In addition, PHF14 depletion has been revealed to inhibit lung and bladder cancer cell proliferation and tumorigenesis." (PMID 37007943, 2023). "In addition, PHF14 promotes tumor cellular epithelial–mesenchymal transition (EMT) and enhances the proliferation and invasiveness of bladder cancer." (PMID 31798343, 2019). "Furthermore, we suggest a possible regulatory mechanism through the sponging of miR-590 by LINC00612, leading to upregulation of PHF14, promoting tumor cellular EMT and enhancing the proliferation and invasion of bladder cancer cells." (PMID 30940184, 2019).
glioblastoma (4 papers, 2019 to 2024). The most malignant astrocytic tumor (WHO grade IV). "This study investigates the role and the underlying mechanisms of PHF14 in GBM (glioblastoma multiforme)." (PMID 31798343, 2019). "The Wnt signaling pathway is implicated in the progression of OFMT and glioblastoma through the involvement of both PHF1 and PHF14." (PMID 38813086, 2024). "PHF14 emerges as a key regulator in glioblastoma, influencing cancer progression through modulation of the Wnt signaling pathway." (PMID 38813086, 2024). "Moreover, PHF14 and PHF19 are identified as key players in glioblastoma, colorectal, and hepatocellular cancers, influencing crucial pathways such as Wnt, AKT, ERK1/2, and Hedgehog-Gli1." (PMID 38813086, 2024). "Mechanistic insights reveal that PHF14’s regulation of the Wnt pathway alters the expression of key markers in epithelial-mesenchymal transition (EMT) and angiogenesis, highlighting its significance in glioblastoma malignancy and offering a novel therapeutic target avenue." (PMID 38813086, 2024).
respiratory failure (4 papers, 2017 to 2025). The significant impairment of gas exchange within the lungs resulting in hypoxia, hypercarbia, or both, to the extent that organ tissue perfusion is severely compromised. "PHF14 plays an important role in lung development and function, as polymorphisms in this gene have been associated with lizard tolerance to high-altitude hypoxia, and the depletion of PHF14 led to respiratory failure and death in mice." (PMID 40427364, 2025). "Homozygous PHF14 knockout mice died within hours after birth due to respiratory failure, although heterozygous PHF14 knockout animals are healthy and fertile." (PMID 36359362, 2022). "In their study PHF14–null mice died shortly after birth due to respiratory failure." (PMID 28814329, 2017).
colorectal cancer (3 papers, 2017 to 2023). A primary or metastatic malignant neoplasm that affects the colon or rectum. "In colorectal cancer, downregulation of PHF14 could reduce carcinogenesis, and our study also indicated that PHF14 was enriched in tumor samples and was associated with poor prognosis, while the molecular mechanisms were not clear." (PMID 36263018, 2022). "To study the potential role of PHF14 in tumors, we screened PHF14 expression in tumor tissues and their matched non-cancerous tissues from non-small cell lung cancer (NSCLC), hepatocellular carcinoma, colorectal carcinoma and renal cell carcinoma by western blot analysis." (PMID 28160558, 2017).
lung fibrosis (3 papers, 2017 to 2020). "PHF14 is involved in multiple biologic processes including Dandy–Walker syndrome, mesenchyme growth, lung fibrosis, renal fibrosis, persistent pulmonary hypertension, and tumor development." (PMID 32596345, 2020). "PHF14 acts as a transcription inhibitor of the platelet-derived growth factor receptor-α (PDGFRα) and then regulates mesenchyme growth, indicating that PHF14 is a potential target for lung fibrosis treatment." (PMID 32596345, 2020).